GSTP1 (glutathione S-transferase pi 1)
Diseases named in the same sentence as GSTP1 in open-access papers (continued):
Sharing a sentence is not in itself a finding about the gene and the disease.
liver cancer (20 papers, 2008 to 2025). An epithelial or non-epithelial malignant neoplasm that arises from the liver. "In HCC, dysregulation of GSTP1 was observed in liver cancer cell lines, and in more than 77.8% of HBV-associated HCC tissues." (PMID 27367026, 2016). "GSTP1 methylation may reflect underlying epigenetic changes that contribute to the malignant transformation of hepatocytes and the progression of liver cancer." (PMID 40051701, 2025). "Hypermethylation of GSTP1 leads to a loss of function and increases susceptibility to liver cancer." (PMID 38890797, 2024). "GSTP1 hypermethylation was more frequently observed in liver cancer tissue compared to liver tissue from patients with other diseases (P < 0.00001)." (PMID 40051701, 2025). "Increased methylation of GSTP1 results in its inactivation, which promotes the development of liver cancer." (PMID 38890797, 2024). "Recent studies have verified that hypermethylation of GSTP1 inactivates the GSTP1 gene and is a significant contributor to liver cancer." (PMID 37901797, 2023). "It has been reported that the expression of GSTP1 is decreased after treatment with the Pin1 inhibitor ATRA in the liver cancer cell line PLC/Huh-7." (PMID 32010480, 2020). "The effect of GSTP1 overexpression on liver cancer cell proliferation was measured by a Cell Counting Kit-8 (CCK8) assay." (PMID 29507666, 2018). "We also found that GSTP1 overexpression restrained HepG2 and Huh7 liver cancer cell proliferation in vivo and in vitro." (PMID 29507666, 2018). "Interrupting GSTP1 gene expression promoted liver cancer cell proliferation and increased the percentage of cells in S phase by decreasing levels of p21 and p27 and increasing p-Akt." (PMID 29507666, 2018). "In the third phase, we studied functional analysis by altering GSTP1 expression in liver cancer cell lines, and performed in vitro and in vivo experiments to characterize its biological role in HCC progression." (PMID 29507666, 2018). "We concluded that p-Akt can regulate p21 and p27 directly or indirectly in liver cancer cells with different GSTP1 levels." (PMID 29507666, 2018). "Given that GSTP1 suppresses hepatic cancer cell growth in vitro and in vivo, we further confirmed that GSTP1 was a protective factor." (PMID 29507666, 2018). "In this study, we found that SIRT3 decreased GSTP1 in both mRNA and protein levels which suggested SIRT3 regulated GSTP1, at least in part, occurs at a transcriptional level in liver cancer cells." (PMID 27367026, 2016). "Our meta-analysis revealed a pooled odds ratio of 6.64 (95% CI: 2.17–20.38) for the comparison of liver cancer tissue versus liver tissue from patients with other liver diseases, indicating that GSTP1 hypermethylation is significantly more prevalent in HCC tissues." (PMID 40051701, 2025). "The pooled analysis yielded a significant difference in GSTP1 hypermethylation between liver cancer tissue and liver tissue from patients with other diseases, with a combined OR of 6.64 (95% CI: 2.17–20.37), indicating that GSTP1 hypermethylation is more frequently observed in liver cancer tissue." (PMID 40051701, 2025). "Understanding these mechanisms could pave the way for the development of targeted therapies that reverse GSTP1 silencing and restore its protective function in liver cancer cells." (PMID 40051701, 2025). "For example, small molecules or RNA-based therapies could be designed to specifically demethylate the GSTP1 promoter and restore its expression in liver cancer cells." (PMID 40051701, 2025). "Therefore, the up-regulation of GST and GSTP1 in liver cancer promotes the extracellular metabolism of antitumor drugs and reduces their efficacy." (PMID 36611862, 2022). "Moreover, decreasing SNHG9 reduced methylation of the GSTP1 gene and inhibited liver cancer cell proliferation, migration and invasion." (PMID 35887228, 2022).
liver cancer (continued). "We found that GSTP1 overexpression could inhibit liver cancer cell proliferation in vivo and in vitro by arresting cell cycle progression at the G1/S transition." (PMID 29507666, 2018). "We found that GSTP1 could decrease p-Akt in liver cancer cell lines, and speculated that GSTP1 may inhibit AFP expression." (PMID 29507666, 2018). "The clinical significance of GSTP1 suggested that GSTP1 might also influence the biological behavior of liver cancer cells." (PMID 29507666, 2018). "An aberrant hypermethylation of GSTP1 promoter and a subsequently induced lack of GSTP1 mRNA or protein expression were demonstrated in liver cancer cell lines, and in more than 77.8% of HBV-associated HCC tissues, respectively." (PMID 20331903, 2010). "The Forest plot presents the comparison between liver cancer tissue (HCC) and liver tissue from patients with other liver diseases in terms of GSTP1 hypermethylation." (PMID 40051701, 2025). "Relevant studies show that P16, RASSF1A, GSTP1, APC, p15 and SFRP1 genes are significantly hypermethylation in HBV positive liver cancer." (PMID 38304027, 2023). "In the present study, NBDHEX was identified as a potentiator of BITC-induced antiproliferation not only in human colorectal cancer HCT-116 cells overexpressing GSTP1 but also in human liver cancer HepG2 cells with no GSTP1/2 expression." (PMID 40943071, 2025).
leukemia (17 papers, 2007 to 2025). A malignant (clonal) hematologic disorder, involving hematopoietic stem cells and characterized by the presence of primitive or atypical myeloid or lymphoid cells in the bone marrow and the blood. "The study reported that the GSTP1 rs1695 GG genotype (GG vs. A) was associated with an elevated risk of neurological toxicity during the continuation phase of leukemia therapy (p = 0.006; OR = 2.70; 95%CI = 1.18–6.25)." (PMID 40430876, 2025). "Induction of leukemia and neurotoxicity by chemotherapy is apparently curbed by strictly opposite GSTP1 polymorphisms." (PMID 18162130, 2007). "Emodin can effectively inhibit the expression of GSTP1, thereby reducing the incidence of glutathione-related resistance in human leukemia." (PMID 39346898, 2024). "GSTP1 polymerisation was detectable and was followed by an increased apoptotic rate of the leukaemia cells." (PMID 26569224, 2015). "The levels of FGA and GSTP1 protein differed among the leukemia cells in distinct ALL groups and normal cells by immunoblotting." (PMID 25317080, 2014). "Previous work of our laboratory has demonstrated that curcumin blocks DNA interaction of transcription factors AP-1 and NK-κB with the glutathione S-transferase (GSTP1-1) promoter region in K562 leukemia cells and consequently prevents transcription of GSTP1-1 gene." (PMID 20944521, 2010).
diabetes (16 papers, 2015 to 2025). "Glutathione-S-transferase including GSTMI, GSTM1, and GSTP1 are important genes and their association with diabetes has been investigated in two meta-analysis studies." (PMID 26587547, 2015). "When GST genotypes distribution in COVID-19 patients and controls was assessed including adjustment for age, gender, smoking habit, and comorbidities, comprising hypertension, obesity, and diabetes, significant association remained for GSTP1 (rs1695) and GSTM3 (rs1332018) polymorphisms." (PMID 34988113, 2021). "Namely, carriers of the heterozygous GSTP1*CT rs1138272 genotype were in 3.4-fold higher odds compared to the carriers of the GSTP1*CC genotype to develop diabetes (OR = 3.43, 95%CI = 1.53–7.70, p = 0.003)." (PMID 36676788, 2023). "Among six investigated GST polymorphisms, a significant association between GST genotype and susceptibility for development of diabetes mellitus was found for the GSTM1, GSTT1, GSTP1 (rs1138272) and GSTO1 (rs4925) polymorphisms." (PMID 36676788, 2023). "The parameters which helped in identifying the severity, leading to poor prognosis, were neutrophil:lymphocyte higher than 4, high CRP, low SOD3 values and high GSTp1 values, and diabetes mellitus as a co-morbidity." (PMID 35314591, 2022). "An anticipated increase in GSTp1 levels, or replenishing the anti-oxidant, points to the pathophysiological bases of increasing severity with age, sex, and co-morbidities like diabetes." (PMID 35314591, 2022). "We found no significant statistical association between GSTM1, GSTT1, and GSTP1 genotypes and the presence of DSPN in patients with diabetes mellitus." (PMID 26435566, 2015). "Eleven genes in the Glutathione metabolism pathway (Gpx7, Gss, Gsta3, Gstm2, Gstm5, Gstm7, Gsto1, Gstp1, Gstt1, Gstt2 and Mgst2) were observed in type 2 diabetes mellitus." (PMID 25788156, 2015). "There was a significant association (p < 0.05) of SOD3 and GSTp1 values with ferritin and Zn in diabetes alone, diabetes with hypertension, and no co-morbidities subgroups." (PMID 35314591, 2022). "Similarly, genes ESR1, SERPINE1 and VEGFA are shared across diabetes (EGFR, GSTP1, SERPINE1, ESR1, VEGFA and EGF) and obesity (CCND1, SERPINE1, ESR1 and VEGFA), which is in line with previous reports that obesity is a risk factor of diabetes." (PMID 31835887, 2019). "In the present study, we observe that in diabetes, expression of NAD(P)Hdehydrogenase 1 (Nqo1) and glutathione S-transferase P (Gstp1) is significantlydownregulated in RMVs while it is not changed in BMVs." (PMID 36606460, 2023). "Those with co-morbidities such as diabetes and hypertension are in a state of oxidative stress, and infection with COVID-19 increases this oxidative stress, overwhelming the oxidative system, as seen in the present study, with decreased SOD3 and increased GSTp1 levels." (PMID 35314591, 2022).
prostate tumors (16 papers, 2006 to 2024). "From these data, it can be seen that C9 methylation at the studied locus of the GSTP1 gene was the most characteristic event associated with the development of prostate tumors, compared to methylation at other single positions of the gene locus." (PMID 34944854, 2021). "The lack of mGSTP1 selection in the final model is in agreement with the large (n = 367) study by Vasiljevic and colleagues, in which prostate tumour GSTP1 methylation levels were associated with PCSM in univariable Cox analysis but eliminated in selection for the final multivariable Cox model." (PMID 39744075, 2024). "The CpG island promoter region of GSTP1 is typically unmethylated in normal prostate tissue DNA but largely hypermethylated in prostate tumour tissue DNA." (PMID 39744075, 2024). "Only the variable GSTP1.T3.T13 allowed the complete separation of HDs from patients with prostate tumors." (PMID 34944854, 2021). "The analysis of the WGBS data allowed us to detect the GSTP1.T3.T13 variable, which provided a complete separation of HDs from patients with prostate tumors." (PMID 34944854, 2021). "Increased methylation levels of HOXD3 and GSTP1 are observed in prostate tumors and are correlated with aggressive PCa and/or adverse clinical outcomes." (PMID 30470249, 2018). "Analyzing potential molecular reasons, we found in RP-PCa and RP-BPH in comparison to TUR-BPH a significant hypomethylation of IGF2-DMR0, which coincided with hypermethylation of GSTP1-promoter, a prominent marker of prostate tumors." (PMID 29017567, 2017). "LNCaP cells and the great majority of clinical prostate tumors are known to have the π-class glutathione S-transferase gene (GSTP1) silenced due to promoter hypermethylation." (PMID 27034170, 2016). "We obtained DNA from NTAT in paraffin-embedded prostate tumour tissues and used probe real-time PCR to analyse methylation of the glutathione S-transferase (GSTP1) and adenomatous polyposis coli (APC) gene promoters." (PMID 23874531, 2013). "There was a high prevalence of both APC methylation (82.2%) and GSTP1 methylation (84.1%) in prostate tumour tissue." (PMID 23874531, 2013). "It is likely the methylation-associated silencing of multiple genes in different cellular pathways integrated by GSTP1 has a role in the progression of prostate tumors." (PMID 18194557, 2008). "All the reads overlapping the investigated locus of the GSTP1 gene were pooled into the two groups, i.e., the normal group (prostate biopsy samples and primary prostate epithelial cell samples) and the cancer group (prostate tumor biopsy)." (PMID 34944854, 2021). "Previously, it was believed that the methylation of the promoter region of the GSTP1 gene in the genomic DNA isolated from prostate tumor tissue was close to 100%; however, using bisulfite sequencing, it was shown that this gene is methylated in 86% of prostate tumor tissues." (PMID 34944854, 2021). "All prostate tumor biopsies obtained prior to HT, showed GSTP1-HM (8/8)." (PMID 16803634, 2006). "For example, SHF, FAXDC2, GSTP1, ZNF154, and KLF8 genes had hypermethylated promoters and silenced gene expression across the prostate tumor samples compared to normal prostate samples." (PMID 36937425, 2023). "Of the six genes, GSTP1, APC, RARB, CCND2, and PTGS2 were tumor suppressors identified as having been hypermethylated in prostate tumor tissues." (PMID 36937425, 2023). "The three genes, i.e., GSTP1, RNF219, and KIAA1539, which are shown to change the methylation status of prostate tumor patients, were studied." (PMID 34944854, 2021). "These were attenuated after adjustment for methylation in prostate tumour tissue, and after adjustment for Gleason score (HR = 1.91, 95% CI: 1.03–3.56 for APC and HR = 1.60, 95% CI: 0.80–3.19 for GSTP1)." (PMID 23874531, 2013). "However, GSTP1 and PPARG were down-regulated in PTC but up-regulated in the profiled prostate tumor." (PMID 38790250, 2024).
prostate tumors (continued). "GSTP1 is overexpressed in breast, colon, lung, and prostate tumors, where it contributes to tumor progression and drug resistance; however, the role of GSTP1 in pancreatic ductal adenocarcinoma (PDAC) is not well understood." (PMID 32526885, 2020). "Numerous studies investigating GSTP1, RARB and RASSF1 DNA promoter methylation have reported that hypermethylation in prostate tumour tissue may represent a biomarker of early cancer diagnosis, in accordance with our results." (PMID 27576364, 2016).
neuropathy (15 papers, 2008 to 2025). A disorder affecting the nervous system that manifests with pain, tingling, numbness, and/or muscle weakness. "Older age, hyperglycemia, and obesity or poor nutritional status, such as single-nucleotide polymorphisms (SNPs) in the FGD4, EPHA5, and FZD3 genes and ABCB1 and GSTP1 polymorphisms, have been associated with the development of taxane-related neuropathy." (PMID 33922821, 2021). "Specifically, the polymorphism Ile105Val of the GSTP1 gene, encoding glutathione transferase P1, has been associated with a decreased risk of developing severe oxaliplatin-related cumulative neuropathy." (PMID 28620280, 2017). "The study revealed that polymorphisms of ERCC1, C118T, and GSTP1 Ile105Val made patients more susceptible to oxaliplatin‐induced neuropathy." (PMID 28127506, 2017). "The GSTP1 Ile105Val polymorphism was previously purported to be associated with less neuropathy and clinical outcomes related to oxaliplatin." (PMID 28640195, 2017). "ABCC2 and GSTP1 were associated with both platinum- and taxane-induced neuropathy; CYP2C8 was associated with both taxane- and platinum/taxane-induced neuropathy; and ERCC1 was associated with platinum- and platinum/taxane-induced neuropathy." (PMID 26269716, 2015). "Homozygous carriers of the rs1695 (313A > G) variant G-allele in GSTP1 have been associated with neuropathy in 90 patients receiving oxaliplatin-based chemotherapy." (PMID 25881102, 2015). "The results of this study suggested that the 105Val allele variant of the GSTP1 gene confers a significantly decreased risk of developing severe OX-related cumulative neuropathy." (PMID 18797464, 2008). "The GSTP1 AA genotype was associated with higher levels of Hg and the heterozygotic genotype (GSTP1 GA) was associated with a higher chance of having an abnormal somatosensory sign and neuropathy burden." (PMID 36851015, 2023). "In a group of 64 evaluable patients receiving a minimal cumulative dose of 500 mg m−2 of OX, the cumulative neuropathy grade 3 was significantly more frequent in patients who were homozygous for the GSTP1 105Ile allele than in patients homozygous or heterozygous for the 105Val allele." (PMID 18797464, 2008). "We analysed whether the GSTP1 Ile105Val polymorphism was associated with OX-related cumulative neuropathy in this group of patients." (PMID 18797464, 2008). "Indeed, in vitro experiments in Escherichia coli carrying different GSTP1 mutations demonstrated altered cytotoxicity, suggesting that GSTP1 polymorphisms could be predictors for the development of cumulative neuropathy." (PMID 28620280, 2017). "A Japanese study of colorectal cancer patients treated with oxaliplatin‐based chemotherapy estimated the pharmacogenetic correlation between neuropathy and polymorphisms of the excision repair cross‐complementation Group 1 (ERCC1) and glutathione‐S‐transferases pi 1 (GSTP1) genes." (PMID 28127506, 2017). "We found statistically significant associations of four SNP markers (rs4646316, rs4380755, rs5008499, and rs6591256) in or near COMT, TPMT, and GSTP1 with neuropathy and five SNP markers (rs3788306, rs12189790, rs17420046, rs6938294, and rs6912842) with ototoxicity at the nominal p-value of 0.05." (PMID 23248619, 2012).
breast tumors (14 papers, 2007 to 2024). "GSTP1 overexpression has been associated with lower breast tumor reduction among patients treated with neo-adjuvant docetaxel or paclitaxel." (PMID 35501422, 2022). "Loss of GSTP1 expression and its potential role in breast carcinogenesis was observed in high proportion of breast tumors." (PMID 24093668, 2013). "We found that the positive rate of GSTP1 expression was significantly higher in smaller tumors (P=0.023) after calculating the association between GSTP1 protein expression and clinicopathological data of breast tumors." (PMID 28978147, 2017). "In our previous studies, we showed that in a cohort of locally-advanced primary breast tumors treated with an anthracycline-based monotherapy, the methylation status of GSTP1 was positively associated with overall survival and independent of other known clinical and histopathological parameters." (PMID 26393654, 2015). "For example, subgroup 10 gathered breast tumours in which the GSTP1 and SERPINB5/maspin as well as the MAD2L1 and MYC genes, which specify basal-type adenocarcinomas, were over-expressed." (PMID 17338809, 2007). "The expression of GSTP1 is higher in the group of chemoresistant breast tumor cells, which may be reflected in the therapeutic response of patients to treatment." (PMID 35204496, 2022). "The expression of the GSTP1 protein in 175 cases of breast tumors was obtained by IHC." (PMID 28978147, 2017). "Moreover they found that promoter hypermethylation of RASSF1A and GSTP1 was more frequent in ER-positive than in ER-negative tumours in both early and advanced breast tumours." (PMID 20056007, 2010). "Additionally, because of its detoxifying effects on the anticancer agents, GSTP1 may also affect the sensitivity of breast tumors to chemotherapy, emerged as a novel therapeutic target." (PMID 26585467, 2015). "Krassenstein and colleagues studied the methylation patterns of a six-gene panel (GSTP1, RAR-β, RASSF1A, DAP-kinase, p16INK4a and p14ARF) in 22 paired breast tumour and nipple aspirate fluid (NAF) DNA samples." (PMID 17324252, 2007).